DSC1 (desmocollin 1)
Diseases named in the same sentence as DSC1 in open-access papers (continued):
Sharing a sentence is not in itself a finding about the gene and the disease.
pemphigus vulgaris (1 paper, 2014). Pemphigus is a group of chronic autoimmune skin diseases characterized by blister formations on the outer layer of the skin and the mucous membranes. "Furthermore, PKP3 binds in vivo to several other primary pemphigus vulgaris autoantigens including DSG3, DSG1, DSC1, and DSC3." (PMID 24988487, 2014).
psoriasis (1 paper, 2023). An autoimmune condition characterized by red, well-delineated plaques with silvery scales that are usually on the extensor surfaces and scalp. "In the psoriasis lesional skin, high expression of desmocollin 2 (DSC2) and desmoglein 3 (DSG3) was also observed, in contrast to the low expression of desmocollin 1 (DSC1) and desmoglein 1 (DSG1)." (PMID 36841845, 2023).
schizophrenia (1 paper, 2022). A major psychotic disorder characterized by abnormalities in the perception or expression of reality. "Other susceptibility genes of schizophrenia such as desmocollin 1 (DSC1) and neuregulin 1 (NRG1) had also been identified to play a vital role in regulating neuronal progenitor proliferation." (PMID 36313621, 2022).
skin cutaneous melanoma (1 paper, 2025). "Besides, DSC1 is significantly associated with infiltration by most immune cells; HOPX expression is linked to immune processes and shows high enrichment of T cells, suggesting it could serve as an immune checkpoint in skin cutaneous melanoma." (PMID 41199193, 2025).
tumor (11 papers, 2006 to 2025). "Other targets included Filaggrin-2, peroxiredoxin 6, Calmodulin-like protein 5, TBCEL-TECTA readthrough protein, Desmocollin 1 and 3, and Desmoplakin variant protein—with implications in diagnosis and tumour progression." (PMID 40725142, 2025). "DSC1 is highly expressed in budding cells at the leading edge of the tumor and associates with poor prognosis in the stem-like, mesenchymal CRC subtypes, while correlates with a more favorable prognosis in the less-aggressive subtypes." (PMID 38263178, 2024). "To study the clinical value of DSC1 expression and its potential association with the invasive front of the tumor, we performed IHC analysis of DSC1 in a tissue microarray containing biopsies of CRC primary tumors that included the leading front." (PMID 38263178, 2024). "In NSCLC, desmosomal proteins plakophilin 1 and DSC1 were previously verified to be associated with tumor development and prognosis." (PMID 36193204, 2022). "Mechanistically, CDH17 appears to facilitate tumour-stromal interactions in GC through homophilic adhesion and interaction with DSC1, thereby promoting migration and invasion." (PMID 41155133, 2025). "Collectively, these results indicate that DSC1 targeting inhibits tumor growth, homing and liver metastasis of CRC mesenchymal cells." (PMID 38263178, 2024). "The clinical relevance of DSC1 in patients is underscored by its expression in budding clusters at the leading edge of the tumor." (PMID 38263178, 2024). "In terms of clinical relevance, IHC analysis of the leading front of tumor samples revealed a high expression of DSC1 in CRC, particularly in migrating clusters formed by 2–3 budding cells." (PMID 38263178, 2024). "In vivo experiments demonstrated that DSC1 silencing reduced tumor growth, liver homing, and metastasis in CRC mesenchymal cells." (PMID 38263178, 2024). "DSC1 had significant difference of expression (p = 0.005) between the blood and tumor tissues in our BLCA samples." (PMID 37876438, 2023). "While DSC1 gene expression in tumor tissues followed the same pattern as in normal bladder tissues, DLX1 expression was the reverse." (PMID 37876438, 2023). "A risk score was generated for each tumor sample with the expression score of GNLY, DSC1, and DLX1, and patients were categorized into two subtypes as high risk and low-risk groups." (PMID 37876438, 2023). "After using the Livak method and normalizing with the ACTB gene, it was found that DLX1 and DSC1 expression was lower in tumor tissues than in blood tissues." (PMID 37876438, 2023). "Klk7 has been implicated in the cleavage of corneodesmosomal proteins, such as Cdsn and Dsc1, during terminal differentiation of the epidermis, and of Dsg1 in tumor cells." (PMID 32457102, 2020). "As before, increases in Dsc1 and Dsc3 mRNA (>2-fold) were detected in a significant number of cases (three of seven and four of seven tumours respectively)." (PMID 17088906, 2006). "Furthermore, DSC1 exhibited significant expression in budding cells within human tumor samples, correlating with poor prognosis in CRC mesenchymal subtypes." (PMID 38263178, 2024). "Interestingly, we observed DSC1 expression in budding cells located at the tumor leading front, enclosed within the stroma compartment." (PMID 38263178, 2024). "In the desmosome, they bind to DSG1 and DSC1 and may thereby act as tumour suppressors by stabilising intercellular adhesion." (PMID 22333708, 2012). "The percentage of cytoplasmic DSC1-positive tumours was 30%." (PMID 22333708, 2012). "Surprisingly, Dsc1 expression was detected in all 16 tumour samples examined." (PMID 17088906, 2006). "De novo expression of Dsc1 and Dsc3 was not entirely dependent on loss of Dsc2 as Dsc1 was expressed in all tumour specimens and Dsc3 was detected in three of eight samples that showed normal levels of Dsc2." (PMID 17088906, 2006).
tumor (continued). "Considering the localization of DSC1 in CRC budding cells, we proceeded to investigate the in vivo consequences of targeting DSC1 using mouse models for tumor growth, liver homing and metastasis." (PMID 38263178, 2024). "A wilcoxon rank test reveals significant difference between the blood and tumor tissues for DLX1 (0.005) and DSC1 (0.02734) genes." (PMID 37876438, 2023). "The expression of the four target genes (MDGA2, DLX1, DSC1, and GNLY) was investigated in tumor tissues and paired blood samples from 10 BLCA patients who were enrolled in the current study." (PMID 37876438, 2023). "Immunohistochemistry of ADAMTS1, DSC1, RNF39, CD3 and LDB3 was performed to evaluate protein expression in tumor cells." (PMID 36333410, 2022). "The adhesive characteristic of DSC1, together with its presence in CRC budding cells at the tumor front, might be relevant for the establishment of circulating tumor cell (CTC) clusters, a pivotal factor in the metastatic spread." (PMID 38263178, 2024). "Additionally, a parallel staining of DSC1 and CDH17 in serial sections revealed a significant correlation between DSC1 and CDH17 expression at the tumor." (PMID 38263178, 2024). "When DSG1 (membrane) and DSC1 (cytoplasmic) were categorised as one variable, the outcome for the patients with tumours staining positive for both DSG1 membranous and DSC1 cytoplasmic protein was significantly worse than for the patients with no staining for DSG1 and DSC1." (PMID 22333708, 2012). "Furthermore, KLK7 may stimulate tumor cell invasion and metastasis through cleaving extracellular matrix (ECM) proteins and several adhesion molecules, such as desmoglein-1 and desmocollin-1." (PMID 33087135, 2020).
cancer (8 papers, 2006 to 2024). A tumor composed of atypical neoplastic, often pleomorphic cells that invade other tissues. "Increased amounts of message encoding both Dsc1 and Dsc3 were detected in cancer specimens." (PMID 17088906, 2006). "Moreover, DSC1 was found to positively influence β-catenin, c-myc and cyclin D1 signaling pathways leading to cancer progression." (PMID 37620794, 2023). "Previous studies suggested DSC1 to play a role in progression of various cancer diseases." (PMID 37620794, 2023). "A study on CRC cells shows Dsc2 is switched to Dsc1 and Dsc3 during cancer development." (PMID 35194111, 2022). "Univariate analyses identified, among others, negative membranous DSG1 staining (P=0.009), negative cytoplasmic DSC1 staining (P=0.012) and negative DSG1 (membranous)+negative DSC1 (cytoplasmic) staining (P=0.004) to be associated with improved cancer-specific survival (CSS)." (PMID 22333708, 2012).
dermatosis (1 paper, 2023). "IgA Dscs ELISAs were also established that successfully detected IgA anti‐Dsc1 autoantibodies in SPD‐type intercellular IgA dermatosis." (PMID 36578135, 2023).
infection (1 paper, 2020). The state of being infected such as from the introduction of a foreign agent such as serum, vaccine, antigenic substance or organism. "Nematode infection studies and whole transcriptome analyses using the Arabidopsis mutants showed that DSC1 and WRKY19 co-regulate susceptibility of Arabidopsis to M. incognita." (PMID 32054439, 2020). "However, this could indicate that no de novo synthesis of DSC1 is required for a role in regulating nematode susceptibility, or that we were not able to detect a local change in gene expression at the infection site due to the use of whole roots as input for the qRT-PCR analysis." (PMID 32054439, 2020).
DSC1 also shares sentences with these, for which no sentence is quoted: pemphigus foliaceus (2 papers); periodontitis (2); adenocarcinoma (1); cervical cancer (1); cervical tumours (1); dyslipidemia (1); ectodermal dysplasia (1); Fibroadenoma (1); gastric cancer (1); Hailey-Hailey disease (1); head and neck squamous cell carcinoma (1); skin cancer (1); squamous cell carcinoma (1).